CXCR4 (C-X-C motif chemokine receptor 4)
Diseases named in the same sentence as CXCR4 in open-access papers (continued):
Sharing a sentence is not in itself a finding about the gene and the disease.
CNS tumors (1 paper, 2022). "Also, CXCR4 was associated with the immune response of other tumors, and anti-CXCR4 union and anti-PD-1 immunotherapies are used in treating other CNS tumors, which further confirmed that CXCR4 is related to immune infiltration." (PMID 35967388, 2022).
overlap syndromes (1 paper, 2018). "Patients with overlap syndromes revealed markedly increased ab levels compared with HD (p = 0.056); 25.5% of the dSSc patients have anti-CXCR4 ab levels above the 95th percentile of the HD." (PMID 29566745, 2018).
psychiatric disorder (1 paper, 2021). A disorder characterized by behavioral and/or psychological abnormalities, often accompanied by physical symptoms. "Moreover, differential CXCR4 protein expression is evidenced in other psychiatric disorders and physiological system dysregulation as well." (PMID 33647040, 2021).
CXCR4 also shares sentences with these, for which no sentence is quoted: acute myocardial infarction (17 papers); bone cancer (9); B-cell acute lymphoblastic leukemia (6); chronic atrophic gastritis (5); Cushing syndrome (4); mycosis fungoides (4); alveolar rhabdomyosarcoma (3); chronic leukemia (3); Huntington disease (3); Lewy body dementia (3); lung disease (3); lung squamous cell carcinoma (3); monocytic leukemia (3); papillary renal cell carcinoma (3); rectal tumors (3); Sézary syndrome (3); vitamin D deficiency (3); amyotrophic lateral sclerosis (2); anaplastic large cell lymphoma (2); arteriovenous malformations (2); bone sarcoma (2); Cachexia (2); chronic heart failure (2); chronic periodontitis (2); combined immunodeficiency (2); coronary artery stenosis (2); cystic fibrosis (2); diabetic cardiomyopathy (2); diabetic foot ulcer (2); Encephalopathy (2).
A further 201 diseases each share a sentence with CXCR4 in 2 papers or fewer.